TM2D1 (TM2 domain containing 1)
Description:
May participate in amyloid-beta-induced apoptosis via its interaction with beta-APP42.
Synonyms: BBP
Tractability: Antibody: UniProt predicts a signal peptide or a membrane-spanning region; its Gene Ontology location is reachable by antibodies, with medium confidence. PROTAC: ubiquitination databases record sites on it.
Gene: Protein-coding gene on chromosome 1 (61,673,636 to 61,725,423, reverse strand). Ensembl gene ENSG00000162604.
Subcellular location: Membrane
Subcellular location (Human Protein Atlas): Nucleoplasm; Vesicles
Gene Ontology:
Molecular function: protein binding; amyloid-beta binding; G protein-coupled receptor activity
Biological process: apoptotic signaling pathway; G protein-coupled receptor signaling pathway
Cellular component: membrane; plasma membrane
Genetic constraint (gnomAD): Loss-of-function variants: 7 observed, 11.98 expected, observed/expected ratio (o/e) 0.58, 90% interval 0.33 to 1.1. The upper end of that interval is the gene's LOEUF score, 1.1, which puts it in group 4 of 6, group 1 being the genes least tolerant of losing a copy. Missense variants: 145 observed, 155.37 expected, observed/expected ratio (o/e) 0.93, 90% interval 0.81 to 1.07. Synonymous variants: 57 observed, 64.35 expected, observed/expected ratio (o/e) 0.89, 90% interval 0.71 to 1.1.
Homologues: Orthologues: chimpanzee TM2D1 (99% identical), macaque TM2D1 (97% identical), rabbit TM2D1 (90% identical), mouse Tm2d1 (85% identical), rat Tm2d1 (83% identical), guinea pig TM2D1 (83% identical), dog TM2D1 (76% identical), pig TM2D1 (73% identical), tropical clawed frog tm2d1 (66% identical), zebrafish tm2d1 (60% identical), Drosophila melanogaster bisc (37% identical), Caenorhabditis elegans Y66D12A.21 (32% identical). Paralogues in human: TM2D3 (29% identical), TM2D2 (26% identical).
Diseases named in the same sentence as TM2D1 in open-access papers:
TM2D1 is named in the same sentence as 7 diseases in open-access papers, as found by Europe PMC text mining. Sharing a sentence is not in itself a finding about the gene and the disease. The quoted sentences say what the papers report.
sarcopenia (1 paper, 2025). Progressive decline in muscle mass due to aging which results in decreased functional capacity of muscles. "From a clinical perspective, the potential of ENSA, FAM43A, MDH2, NUBP1, SAMM50, and TM2D1 as biomarkers is promising, as they may be measurable in peripheral blood or muscle biopsy specimens to support early screening and individualized diagnosis of AS patients at risk of sarcopenia." (PMID 41204493, 2025).
TM2D1 also shares sentences with these, for which no sentence is quoted: breast carcinoma (1 paper); dementia (1); infection (1); neuroblastoma (1); Salmonella Infections (1); tumor (1).